SPTY2D1 (SPT2 chromatin protein domain containing 1)
Description:
Histone chaperone that stabilizes pre-existing histone tetramers and regulates replication-independent histone exchange on chromatin. Required for normal chromatin refolding in the coding region of transcribed genes, and for the suppression of spurious transcription. Binds DNA and histones and promotes nucleosome assembly (in vitro). Facilitates formation of tetrameric histone complexes containing histone H3 and H4. Modulates RNA polymerase 1-mediated transcription (By similarity). Binds DNA, with a preference for branched DNA species, such as Y-form DNA and Holliday junction DNA.
Synonyms: FLJ39441; DKFZp686I068; Spt2
Tractability: PROTAC: UniProt records ubiquitination sites on it; ubiquitination databases record sites on it; its protein half-life has been measured.
Gene: Protein-coding gene on chromosome 11 (18,606,403 to 18,634,791, reverse strand). Ensembl gene ENSG00000179119.
Subcellular location: Nucleus, nucleolus
Subcellular location (Human Protein Atlas): Nucleoli; Nucleoplasm
Gene Ontology:
Molecular function: DNA binding; histone binding; histone chaperone activity; RNA polymerase I core binding
Biological process: heterochromatin formation; nucleosome assembly; regulation of DNA-templated transcription; transcription by RNA polymerase I
Cellular component: nucleolus; nucleoplasm
Genetic constraint (gnomAD): Loss-of-function variants: 19 observed, 61.5 expected, observed/expected ratio (o/e) 0.31, 90% interval 0.22 to 0.45. The upper end of that interval is the gene's LOEUF score, 0.45, which puts it in group 2 of 6, group 1 being the genes least tolerant of losing a copy. Missense variants: 706 observed, 857.95 expected, observed/expected ratio (o/e) 0.82, 90% interval 0.77 to 0.88. Synonymous variants: 281 observed, 295.97 expected, observed/expected ratio (o/e) 0.95, 90% interval 0.86 to 1.05.
Homologues: Orthologues: chimpanzee SPTY2D1 (99% identical), macaque SPTY2D1 (97% identical), rabbit SPTY2D1 (87% identical), dog SPTY2D1 (85% identical), guinea pig SPTY2D1 (85% identical), pig SPTY2D1 (83% identical), rat Spty2d1 (82% identical), mouse Spty2d1 (80% identical), zebrafish spty2d1 (36% identical). Paralogues in human: CCDC61 (12% identical).
Diseases named in the same sentence as SPTY2D1 in open-access papers:
SPTY2D1 is named in the same sentence as 4 diseases in open-access papers, as found by Europe PMC text mining. Sharing a sentence is not in itself a finding about the gene and the disease. The quoted sentences say what the papers report.
breast carcinoma (1 paper, 2023). "Two intronic AIMs (rs13267382: chr8, LINC00536; rs9952980: chr18, SLC14A2) and two intergenic AIMs (rs10832963: chr11, SPTY2D1 - SRSF3P1; rs11814448: chr10) were also found to be associated with breast cancer in samples of European and Asian ancestry." (PMID 36911410, 2023).
diabetes (1 paper, 2022). "Among the four genes (PHIP, TRPM3, SPTY2D1 and TSPO) associated with fasting insulin and combined into a genetic risk score, we showed that carriers of insulin increasing risk alleles had higher odds of developing diabetes and impaired fasting glucose at follow-up." (PMID 35665752, 2022).
SPTY2D1 also shares sentences with these, for which no sentence is quoted: osteosarcoma (1 paper); tumor (1).